MMP9 (matrix metallopeptidase 9)
Diseases named in the same sentence as MMP9 in open-access papers (continued):
Sharing a sentence is not in itself a finding about the gene and the disease.
fibrosis (77 papers, 2005 to 2026). the formation of excess fibrous connective tissue in an organ or tissue in a reparative or reactive process. "MMP-9 modulates senescence-associated inflammation to alleviate age-related cardiac fibrosis and diastolic dysfunction, induces the accumulation of ventricular macrophages, promotes macrophage polarization and results in cardiac aging and inflammation." (PMID 41197720, 2025). "Fibrosis and chronic inflammation exemplify disease momentum in which sustained MMP-9 activity transitions from adaptive to pathogenic." (PMID 41304763, 2025). "MMP9 deficiency in cystic kidney worsen cystic kidney diseases by decreasing renal function, favoring cyst expansion and fibrosis." (PMID 38039285, 2023). "MMP-9-deficiency mice led to reduced peribronchial fibrosis in an allergen-challenged fibrosis model and airway remodeling." (PMID 38235425, 2023). "Higher Interleukin-6 (IL-6) increased (p = 0.0321) and lower Matrix Metalloproteinase-9 (MMP-9) serum levels (p = 0.0031) were associated with higher fibrosis as measured by Fibroscan® in multivariable regression analysis." (PMID 34813621, 2021). "Because matrix metalloproteinase-2 (MMP2) and matrix metalloproteinase-9 (MMP9) are associated with fibrosis in diabetic cardiomyopathy, we examined the expression and activity of MMP2 and MMP9." (PMID 34385917, 2021). "MMP-9, a proteinase secreted by macrophages and regulating extracellular matrix degradation, is associated with fibrosis, indicating the therapeutic efficacy of thMSC-EVs in fibrosis." (PMID 39112999, 2024). "In addition to the aggravated cystic phenotype, the percentage of fibrosis was noticeably increased in MMP9 deficient mice." (PMID 38039285, 2023). "We previously demonstrated that LCN2 promotes hepatic fibrosis in HFD-fed ob/ob mice by activating HSCs via LCN2/MMP9/STAT3-mediated signaling." (PMID 39832399, 2025). "In all, PFD alleviates the level of MMP9 expression in silicosis lungs to exert its anti-silicosis fibrosis effect." (PMID 40470053, 2025). "Cluster analysis with further regression analysis of fibrogenesis key markers of infection dynamics showed that Jagged1, Mmp9, as well as their interaction, have the greatest contribution to the development of cholangio- and periductal fibrosis." (PMID 36355906, 2022). "It is thus reasoned that the reduced cardiac fibrosis in MKP-5 deficient mice is attributed, at least in part, to the increased expression of Mmp-9 in Ly6Clow cardiac macrophages." (PMID 34992607, 2021). "Emerging candidate biomarkers for CKD progression include surrogates of tubulointersitital injury (NGAL, IL-18, KIM-1, EGF), tubulointerstitial fibrosis (MMP-9, PIIINP, TGF-β1, BMP-7), and inflammation (MCP-1, TNFR 1/2, suPAR)." (PMID 33108507, 2021). "We observed that the increased pro-MMP-9 signal in the fibrotic colon occurred concurrently with increased signal in the kidney, which we demonstrate for the first time develops fibrosis in this model." (PMID 33230169, 2020). "Recent data indicate that MMP9 plays a role in the modulation of intestinal fibrosis, and suggest that selective MMP9 inhibition is a promising therapeutic strategy for treatment of penetrating CD30." (PMID 30315190, 2018). "Much research has demonstrated that PAI-1 deficiency in mice can lead to increases in tPA and MMP9 activities and decrease in cholestatic liver fibrosis and that PAI-1 level in fibrosis liver is significantly increased." (PMID 29234445, 2017). "As MMPs are involved in mucosal fibrosis we determined the expression of tissue remodeling protease MMP-9 and the tissue inhibitor of metalloproteinases TIMP-1 in intestinal transplants by real-time PCR." (PMID 29247242, 2017). "MMP-9 expression was decreased in the fibrosis model groups, and was increased by quercetin treatment." (PMID 28839277, 2017).
fibrosis (continued). "The C4M12a1 and C4M12a3 neo-epitopes were both released by MMP-2 and MMP-9, gelatinases with a high specificity for type IV collagen and known to be up-regulated in fibrosis." (PMID 24376856, 2013). "Expression of genes critical for cardiac fibrosis, such as αSMA, fibronectin, vimentin and MMP9 was significantly increased in old αMHC-Cre/Foxm1fl/fl hearts compared to age-matched controls." (PMID 23144938, 2012). "We previously identified CO3-610, a type III collagen neoepitope generated by matrix metalloproteinase (MMP)-9, and tested its performance as a fibrosis marker in rats with bile-duct ligation." (PMID 21813019, 2011). "Anti‐MMP‐9 antibodies were found to neutralize excessive MMP‐9 reducing collagen deposition, suggesting that anti‐MMP‐9 antibodies may be an effective method for dampening fibrosis." (PMID 38023697, 2023). "Because periostin can increase MMP9 expression, but also aggravates cyst growth and fibrosis in pcy mouse cystic kidneys, we first ask whether its expression could be modified in the Nek8jck (jck) model." (PMID 38039285, 2023). "More MMP-9 and less TIMP-1 levels might have anti-fibrotic roles, and therefore be beneficial to resolve PSC-associated fibrosis." (PMID 27600527, 2016). "One possible mechanistic link by which MMP-9 might contribute to ventricular arrhythmia is cardiac fibrosis and intercellular uncoupling, whereas cardiomyocyte-specific mechanisms, such as calcium dysregulation, might represent an alternative hypothesis." (PMID 27966586, 2016). "At this timepoint, the simGCRsim-IR mice had elevated levels of cardiac fibrosis, inflammation, and hypertrophy markers Tgfβ1, Mcp1, Mmp9, and βmhc, suggesting that space-type IR may induce the cardiac remodeling processes that are commonly associated with diastolic dysfunction." (PMID 36982525, 2023). "Reduction in hyperlipidemia‐induced cardiac damage were observed after luteolin treatment via suppression of lipid deposition (LOX‐1 and CD36) and cardiac fibrosis (MMP2, MMP9, Collagen I, Collagen III, and TGF‐β)." (PMID 39830909, 2025). "As a result of this, ISO-injured mice presented with a significant reduction in LV MMP-13/TIMP-1 (by ~ 60%), MMP-9/TIMP-1 (by ~ 55%) and MMP-2/TIMP-2 (by ~ 65%) ratios at day 14 post-injury, in line with the increased LV fibrosis in these mice." (PMID 41382190, 2025). "Compared with those of 12- and 32-week-old mice, the kidneys of the model mice exhibited prominent fibrosis characteristics, accompanied by numerous fibrous septa and collagen deposition, increased COL1A1 expression, and decreased MMP9 expression." (PMID 39661589, 2024). "Decreased MMP-2 and MMP-9 and increased TIMP-1 were found as part of the mechanism of developed fibrosis with IL-19 KO." (PMID 37509702, 2023). "Cardiac fibrosis and apoptosis were histologically studied through Picrosirius red and TUNEL assay, respectively and quantified through pro-collagen-1α1, MMP-9 and Caspase-3 expression." (PMID 34301253, 2021). "In LX2 fibrosis cells, expression of genes involved in ECM accumulation (TIMP1) and degradation (MMP9, MMP12, MMP13) were notably altered via JT003 exposure." (PMID 33199780, 2020). "The developed LG1M assay detects a degradation fragment of LAMC1 which is released by MMP-9, an MMP known to be highly upregulated in fibrosis." (PMID 30273365, 2018). "The fibrosis of lung was detected by assessment the level of collagen type I (COL1), metalloproteinase-9 (MMP-9) and metalloproteinases-1 (TIMP-1)." (PMID 27191651, 2016). "After MSC transplantation, the increased expression of MMP-2, MMP-9, MMP-13, and MMP-14 has been observed in several fibrosis models." (PMID 25132856, 2014). "In some fibrosis models, MMP-2, MMP-9, and MMP-13 have a lower expression and concentration following treatment with MSCs." (PMID 25132856, 2014).
fibrosis (continued). "A recent study of the relationship between serum MMP-9, TIMP-1 and fibrosis in 50 patients with various chronic liver disease showed that serum levels of MMP-9 in chronic hepatitis patients were low as compared to the controls (P < 0.05)." (PMID 21849046, 2011). "Most interestingly, a mouse model of bleomycin-induced fibrosis showed that the administration of human CCL18 via an adenoviral vector increased TNF-, IFNγ-, MMP-2 and MMP-9 expression and increased lymphocytosis but attenuated unexpectedly the bleomycin-induced collagen deposition." (PMID 38334630, 2024). "Meanwhile, the cardiac fibrosis is also promoted with the featured phenotype of interstitial and perivascular fibrosis, signatured with upregulated Col1a1, Col3a1 and Tgfb expression, along with a significant increase of MMP-2 and surge upregulated active-MMP-9." (PMID 36834504, 2023). "In fibrosis mice, consistently, the expression of genes related to ECM accumulation (TIMP1, MMP3 and MMP8) were decreased and genes involved in ECM elimination (MMP2, MMP9 and MMP13) were notably upregulated after JT003 treatment." (PMID 33199780, 2020). "Results showed that the levels of Col1α1, Col3α1, α-SMA, MMP9 and TIMP1 were decreased while TGF-β was increased in anti-parasite group in comparison to infected group and all of them were decreased in anti-fibrosis group in comparison to both infected group and anti-parasite group." (PMID 21629648, 2011). "Thus, we detected MMP-9 and TIMP-1 protein expression in lung tissue in BLM-induced fibrosis." (PMID 29311918, 2017). "The increased cardiac fibrosis induced by MI was paralleled by significantly increased expression of the pro-fibrotic genes, connective tissue-derived growth factor (CTGF), periostin and fibronectin; expression of matrix metalloproteinase (MMP)-9 also tended to increase in WT (P = 0.05)." (PMID 29192208, 2017). "Taken together, these results suggest that rat liver Mmp9 production and activity may reach their peak during fibrosis, but not cirrhosis." (PMID 21813019, 2011). "Thus by analysis of cleavage fragments generated by MMP-9 of type III collagen, and the development of a specific assay quantifying a validated fragment, novel tools with increased sensitivity and specificity for some types of fibrosis may be developed." (PMID 23249435, 2012). "NONO and MMP-9 expression were positively correlated with multiple clinical and Fibrosis-related pathological indicators, and NONO expression was positively correlated with MMP-9(P<0.05)." (PMID 41163679, 2025).
Alzheimer disease (73 papers, 2010 to 2025). A progressive, neurodegenerative disease characterized by loss of function and death of nerve cells in several areas of the brain leading to loss of cognitive function such as memory and language. "Although MMP-9 has been reported to exert context-dependent neuroprotective effects, such as promoting amyloid-beta clearance in Alzheimer’s disease models our findings suggest that in COPD-associated depression, its pathogenic effects predominate." (PMID 40823578, 2025). "MMP-9 is involved in the breakdown of extracellular matrix and enhanced MMP-9 expression is associated with neuroinflammation and Alzheimer’s disease." (PMID 40875171, 2025). "MMP-2 and MMP-9 are linked to neuroinflammation and neurodegenerative diseases such as Alzheimer’s disease (AD) and multiple sclerosis as well." (PMID 38069361, 2023). "Its degradation, as that of increased enzymatic (MMP-9) activity, can therefore exacerbate cell loss in Alzheimer’s disease." (PMID 36232390, 2022). "Elevated brain levels of MMP3 have been associated with the duration of Alzheimer's disease, and it has been found to increase the activity of MMP9, thereby indirectly promoting aggregation and cerebral accumulation of tau deposits." (PMID 33869630, 2021). "Specifically, apolipoprotein E of astrocytic origin causes an increase in BBB permeability associated with age and Alzheimer’s disease due to the pro-inflammatory effects of cyclophilin and the activation of matrix metalloproteinase MMP-9." (PMID 34796023, 2021). "Matrix metallopeptidase 9 (MMP9) has been implicated in a variety of neurological disorders, including Alzheimer’s disease (AD), where MMP9 levels are elevated in the brain and cerebrovasculature." (PMID 34034683, 2021). "Among these enzymes, abnormal expressions or activations of gelatinases, MMP-2 (gelatinase A) and MMP-9 (gelatinase B), were reported to be associated with numerous disease conditions, such as cancer, cardiovascular diseases and Alzheimer's disease." (PMID 28945763, 2017). "Interestingly, a longitudinal study in individuals with mild cognitive impairment and Alzheimer’s disease reported an association between high MMP-9 levels and declines in cognitive function and hippocampal volumes." (PMID 38431757, 2024). "The MMP-9 expression may be associated with Alzheimer’s disease and the formation of senile plaques and neurofibrillary tangles, suggesting that MMP-9 could be a therapeutic target to treat brain inflammation." (PMID 33261005, 2020). "Additionally, the dysregulation of MMPs has been implicated in the pathology of Alzheimer’s disease (AD), where inhibiting the secretion of MMP-9 from astroglia reduces the proteolytic degradation of amyloid-beta." (PMID 32317959, 2020). "In addition to the association with ALS and PD, MMP-9 has also been linked to Alzheimer’s disease (AD) and Huntington’s disease (HD)." (PMID 24040066, 2013). "MMP9 has a role in the development of sensory circuits during early postnatal life, and misregulated activation of this enzyme is implicated in a number of neurodegenerative disorders, including traumatic brain injury, multiple sclerosis, and Alzheimer’s disease." (PMID 32471213, 2020). "ALS also had significantly higher active MMP-9 in serum than patients with Alzheimer’s disease and higher than Parkinson’s disease or diabetic nephropathy." (PMID 41009467, 2025). "Recent studies have reported that endogenous proteases, including CD10, MMP9, cathepsin D, and cathepsin B, showed fibrinolytic capacity to amyloid-beta fibrils of Alzheimer's disease." (PMID 40302732, 2025). "Our results highlight a shared neuroinflammatory signature across Alzheimer’s disease (AD), Parkinson’s disease (PD), and Huntington’s disease (HD), characterized by the dysregulation of hub genes such as MMP9, S100A8, S100A9, CCL2, and LCN2." (PMID 41614741, 2025).
Alzheimer disease (continued). "Enhanced concentrations of chosen MMPs (including MMP-9) in the cerebrospinal fluid were reported in numerous states, such as Alzheimer’s disease, dementia, and multiple sclerosis." (PMID 39456671, 2024). "On the other hand, an elevated MMP-9 level has also been reported in Alzheimer’s disease and a variety of neurological and inflammatory diseases." (PMID 39135795, 2024). "MMP9 levels are also upregulated in the plasma in both mild cognitive impairment and Alzheimer’s disease patients." (PMID 39635981, 2024). "Matrix metalloproteinases (in particular MMP-2 and MMP-9) were found to be related to hypertension and overexpressed around astrocytes in Alzheimer’s disease, promoting accumulation of amyloid beta (Aβ) plaques." (PMID 39610697, 2024). "Overexpression of MMP-9 has been confirmed in several disorders, including cancers, Alzheimer′s disease, autoimmune diseases, cardiovascular diseases, and dental caries." (PMID 37037467, 2023). "Note that the Alzheimer disease-presenilin pathway identified as the most enriched by the Panther algorithm is related to ECM remodeling (genes included in the pathway: Mmp9, Mmp8, Mmp2, Mmp13, Mmp12)." (PMID 35386010, 2022). "A recent study showed that inhibition of the mTOR pathway by rapamycin leads to the downregulation of MMP9 activity in models of Alzheimer's disease and vascular cognitive impairment." (PMID 31183875, 2020). "In Alzheimer’s disease (AD), the higher levels of MMP-9 have been reported in the plasma and hippocampus." (PMID 30218997, 2019). "Matrix metalloproteinase-9 (MMP-9) expression has been implicated in molecular mechanisms of neurodegenerative disorders, and its abnormal level has been reported in Alzheimer’s disease (AD)." (PMID 30218997, 2019). "Our data is consistent with studies in multiple sclerosis, Alzheimer’s disease and bacterial meningitis where MMP-9 drove BBB dysfunction and neuronal injury." (PMID 29167512, 2017). "The ability of MMP-9 to cleave β-amyloid peptide is particularly interesting because an increase in MMP-9 expression was observed in Alzheimer’s disease patients by several research groups." (PMID 25071472, 2014). "MMP-9 is expressed in the cytoplasm of neurons, neurofibrillary tangles, senile plaques, and vascular walls in brain tissue from patients with Alzheimer's disease." (PMID 22235372, 2011). "In this paper, we discuss various animal models that suggest that the activation of the gelatinases MMP-2 and MMP-9 is involved in pathogenesis of drug dependence, Alzheimer's disease, and epilepsy." (PMID 22235372, 2011). "We speculate that MFXD may exert anti-Alzheimer’s disease effects by regulating the key target MMP9 and related pathways." (PMID 41450541, 2025). "The authors speculate that MMP-9 is involved in the pathophysiology of Alzheimer’s disease at an early stage, potentially through a reduction in mature nerve growth factor." (PMID 38431757, 2024). "FA-induced decreased expression levels of BACE1 and APP and increased expression of MMP2 and MMP9 were found by cellular experiments, and FA may be a potential herbal component for the treatment of Alzheimer’s disease." (PMID 39372201, 2024). "MMP-9, a major component of the vascular basement membrane of arteries, may contribute to the pathogenesis of neurodegenerative diseases such as Alzheimer’s disease (AD), Parkinson’s disease (PD), and amyotrophic lateral sclerosis (ALS)." (PMID 37206663, 2023). "There is a lot of evidence that MMP-9 could represent a pathophysiological link between Alzheimer’s disease (AD)." (PMID 37206663, 2023). "In particular, MMP-9 attracted much attention, first when it was shown to cleave β-amyloid in vitro, followed by the clinical phenomenon that its plasma level is typically increased in Alzheimer’s disease patients." (PMID 36232390, 2022).